ACE (angiotensin I converting enzyme)
Diseases named in the same sentence as ACE in open-access papers (continued):
Sharing a sentence is not in itself a finding about the gene and the disease.
renal failure (125 papers, 2004 to 2026). "The correlation with CS and renal survival is in line with a systemic review of nine RCTs with more than 500 pts, which found that a course of CS reduced the risk for renal insufficiency more than supportive therapy or ACE inhibitors alone in IgAN pts." (PMID 27416024, 2016). "Certain ACE inhibitors containing sulfhydryl groups, like captopril, have been associated with rash, neutropenia, and nephrotic syndrome, especially in patients with renal insufficiency." (PMID 39046229, 2024). "This could be explained that excessive diuresis can increase the risk of hypotension and renal insufficiency with ACE inhibitors due to volume depletion." (PMID 31179336, 2019). "In one strain of ACE-KO mice, there were increases in circulating levels of AcSDKP that was accompanied by a 35 mm Hg decrease in blood pressure, renal insufficiency, and unexpected normocytic anemia associated with an increase in circulating erythropoietin in response to anemia." (PMID 24167502, 2013). "Both ACE inhibitors and ARBs reduce the risk of CVD events and kidney failure in patients with CKD; however, ACE inhibitors appear to be superior to ARBs for that purpose." (PMID 41227089, 2025). "It has also been suggested that early detection of COQ8B nephropathy after supplementation with CoQ10 in combination with ACE inhibitors can slow the progression of renal insufficiency." (PMID 39877334, 2024). "The results were encouraging, suggesting that early treatment with ACE inhibitors can slow the onset of kidney failure by many years." (PMID 38745975, 2024). "This study investigated if the addition of an ACE inhibitor (ACEi) to Ang 1–7 infusion would unmask any beneficial effects of Ang 1–7 on the heart in experimental kidney failure." (PMID 28192475, 2017). "We previously reported that exogenous angiotensin (Ang) 1–7 has adverse cardiac effects in experimental kidney failure due to its action to increase cardiac angiotensin converting enzyme (ACE) activity." (PMID 28192475, 2017). "Patients with renal insufficiency were less likely to receive life-saving medical medications such as anti-platelet agent, β-blocker, ACE inhibitor/ARB, or statin during hospitalization and at discharge." (PMID 22966970, 2012). "Even before the onset of proteinuria, treatment with angiotensin-converting enzyme (ACE) inhibitors could delay the onset of kidney failure and improve life expectancy." (PMID 41557100, 2026). "However, despite treatment with ACE inhibitors, AS patients with a severe phenotype continue to reach kidney failure in their early adult life." (PMID 39429698, 2023). "Underuse of antiplatelet therapy, ACE inhibitors, β-blockers and statins might also be related to a reduced survival rate in patients with renal insufficiency as discontinuation of cardiac medication is itself associated with increased risk of mortality." (PMID 26702638, 2015). "In a subsequent meta-analysis of 1860 non-diabetic patients, it was again shown that ACE inhibition significantly reduced the risk of creatinine doubling or kidney failure." (PMID 20441574, 2010). "A recent meta-analysis of 119 randomized controlled trials in patients with CKD found that ACE inhibitors compared to ARBs were associated with higher probabilities of reducing kidney failure and cardiovascular death and that ACE inhibitors, but not ARBs, reduced all-cause death compared to control." (PMID 34533690, 2023). "However, it should be noted that patients with decompensated liver cirrhosis (Child-Pugh classes B and C) are not ideal candidates for ACE inhibition due to significantly lower arterial blood pressure and increased risk of hepatorenal syndrome–associated renal dysfunction." (PMID 35801591, 2022). "What is more, ACE inhibitors demonstrated significantly greater antiproteinuric effect and the reduction in incidence of CKD and kidney failure in obese and overweight patients than in those with normal BMI." (PMID 35211791, 2022).
renal failure (continued). "In this regard, treatment with ACE inhibitors slows but does not stop the progression to kidney failure in AS and emphasises the urgent need for the discovery of new treatment options." (PMID 39429698, 2023). "In these mice, plasma ACE activity was reduced without evidence of renal insufficiency indicating that the anemia was not the consequence of the renal failure, but the result of a reduction in red-cell mass." (PMID 24167502, 2013). "Our patient was not chronically taking medications that would alter potassium excretion (i.e., ACE inhibitors or potassium-sparing diuretics), and even though mild azotemia was present before surgery, it was not severe enough to question whether renal insufficiency may limit potassium excretion." (PMID 39176395, 2024).
Alzheimer disease (124 papers, 2005 to 2026). A progressive, neurodegenerative disease characterized by loss of function and death of nerve cells in several areas of the brain leading to loss of cognitive function such as memory and language. "Angiotensin-converting enzyme (ACE) is a validated risk locus for developing late-onset Alzheimer's disease (AD)." (PMID 41570992, 2026). "Angiotensin-converting enzyme (ACE), a dipeptidyl carboxypeptidase, is known to cleave amyloid-beta (Aβ), and its reduced activity has been linked to the progression of Alzheimer's disease (AD)." (PMID 42088504, 2026). "Specifically, we found that decreased expression of ACE in blood and brain cortex is linked to increased risk of both schizophrenia and Alzheimer’s disease." (PMID 40281223, 2025). "Mutations in the gene encoding ACE are associated with a wide range of diseases, including the pathophysiology of the entire cardiovascular system, renal failure, psoriasis, and Alzheimer’s disease." (PMID 39456746, 2024). "Whereas decreased ACE expression (accompanied by decreased blood ACE) is becoming a new risk factor for Alzheimer’s disease." (PMID 38790902, 2024). "Systematic analysis of blood ACE levels in patients with all ACE mutations is likely to have clinical significance because available sequencing data will help detect persons with increased risk of late-onset Alzheimer’s disease." (PMID 38255267, 2024). "These selected proteins, which were upregulated in both ACE-inhibitor-treated groups, play important roles in the nervous system and are also associated with Alzheimer’s disease." (PMID 37630190, 2023). "An imbalance in the ACE/ACE2 ratio was implicated in various pathological conditions including Alzheimer’s disease, pulmonary hypertension, cardiovascular, and renal pathology." (PMID 36353605, 2022). "Accordingly, cerebrospinal fluid levels of ACE were associated with an Amyloid-ß42 burden in patients diagnosed with Alzheimer’s Disease." (PMID 35887034, 2022). "ACE inhibitors were found to have strong evidence of a causal relationship with increased Alzheimer’s disease risk in a previous MR study conducted to investigate the use of antihypertensive drugs to treat the disease." (PMID 33417599, 2021). "Despite the benefits of ACE inhibitors, previous studies also have suggested that genetic variants of the ACE gene are risk factors for Alzheimer’s disease (AD) and other neurological diseases, while other variants are associated with reduced risk of AD." (PMID 34947975, 2021). "Many studies among different ethnic populations suggested that angiotensin converting enzyme (ACE) gene polymorphisms were associated with susceptibility to Alzheimer’s disease (AD)." (PMID 34818351, 2021). "The insertion (I)/deletion (D) polymorphism of Angiotensin-Converting Enzyme (ACE) has been associated with longevity and chronic diseases, such as CVDs and Alzheimer's dementia." (PMID 32714484, 2020). "Angiotensin I-converting enzyme, especially its N-terminal active site, can hydrolyse in vitro the Alzheimer amyloid Aβ-peptide that is believed to be causally involved in Alzheimer disease." (PMID 31316987, 2019). "Previous studies have shown the ACE polymorphism to be correlated with cardiovascular disease risk and complications, proliferative diabetic retinopathy, Alzheimer’s disease, and acute macular degeneration." (PMID 30200182, 2018). "The homozygous insertion allele (I) is associated with lower plasma levels of ACE enzyme, and has been linked to the onset and progression of Alzheimer’s disease." (PMID 30200182, 2018). "The ACE polymorphisms rs4291 and rs1800764 have indicated a relationship with the risk of late-onset Alzheimer’s disease (LOAD) and haplotypes of ACE are connected with ACE level in plasma and LOAD risk." (PMID 28336767, 2017).
Alzheimer disease (continued). "The angiotensin-converting enzyme gene (ACE) insertion/deletion (I/D or indel) polymorphism has long been linked to Alzheimer’s disease (AD), but the interpretation of established data remains controversial." (PMID 29176997, 2017). "The brain RAS has been shown to be involved in memory loss associated diseases such as Alzheimer's disease (AD) and cognitive dysfunctions which are preventable by angiotensin converting enzymes (ACE) inhibitors including captopril." (PMID 27830176, 2016). "Our cross-sectional study showed that the interaction between apolipoprotein E4 (ApoE4) and angiotensin converting enzyme (ACE) inhibitors was associated with Alzheimer’s disease (AD)." (PMID 23948883, 2013). "Damaging mutations of the Angiotensin I-converting enzyme (ACE) that result in low ACE levels may increase the risk of developing late-onset Alzheimer’s disease (AD)." (PMID 41009662, 2025). "Furthermore, ACE degrades amyloid β (Aβ), which is associated with the progression of Alzheimer’s diseases." (PMID 40988601, 2025). "ACE inhibitors may be linked to increased risk of Alzheimer’s disease (AD) and frontotemporal dementia while CCBs may be associated with a lower risk of AD." (PMID 39567981, 2024). "Decreased blood ACE activity is becoming a new risk factor for Alzheimer’s disease." (PMID 38790902, 2024). "We present here an example of such an analysis and also describe different mechanisms by which these ACE mutations may initiate Alzheimer’s disease." (PMID 38255267, 2024). "Our analysis suggests several mechanisms by which ACE mutations may be associated with Alzheimer’s disease." (PMID 38255267, 2024). "Therefore, a decrease in tissue ACE activity has been proposed as a possible risk factor for Alzheimer’s disease (AD)." (PMID 38255267, 2024). "Recently, increased female susceptibility to Alzheimer’s disease was found in the carriers of the novel ACE mutation R1279Q which may be explained by significant differences in the conformation of ACE in male and female tissue ACEs." (PMID 36979933, 2023). "It was also suggested that ACE may be protective since elevated ACE levels reduces the risk of global brain atrophy and Alzheimer’s disease." (PMID 37630190, 2023). "ACE polymorphisms are a risk factor for Alzheimer’s disease and age-onset diseases that may contribute to the mortality of older people." (PMID 36834822, 2023). "However, previous observational studies have shown conflicting directions of associations between ACE inhibitors and risk of Alzheimer disease." (PMID 36046424, 2022). "Further work is required to investigate whether therapeutic inhibition of ACE increases risk of Alzheimer disease." (PMID 36046424, 2022). "ApoE4 is considered a major genetic risk factor for late-onset and sporadic Alzheimer disease and incident memory decline, and there is evidence that ACE inhibitors are protective against the risk of Alzheimer’s disease in the absence of ApoE4, but not in the presence of the ApoE4 allele." (PMID 34362026, 2021). "Lower angiotensin-converting enzyme (ACE) activity could increase the risk of Alzheimer’s disease (AD) as ACE functions to degrade amyloid-β (Aβ)." (PMID 24987467, 2014). "Because approximately 4–5% of the general population are carriers of different LoF ACE mutations, we hypothesized that subjects with heterozygous LoF ACE mutations are at risk for the development of Alzheimer’s disease, especially for those LoF mutations that result in reduced ACE activity." (PMID 38255267, 2024). "Therefore, a decrease in tissue ACE activity (either due to constitutive intrinsic mutations or ACE inhibitor treatment) could be associated with Alzheimer’s disease (AD) pathogenesis." (PMID 38255267, 2024). "Importantly, ACE, when altered, is a risk factor gene in Alzheimer’s disease." (PMID 36834822, 2023).
Alzheimer disease (continued). "However, mice models have demonstrated that increased expression of ACE helps to prevent cognitive decline and to protect against amyloid Beta-protein deposits, which if they build up in a brain are a risk factor for the development of Alzheimer’s disease." (PMID 33417599, 2021). "Materials and Methods: We investigated the potential contribution of increased intestinal permeability to handgrip strength (HGS) and physical capacity in patients with Alzheimer's disease (AD) taking ACE inhibitors." (PMID 41754844, 2026). "Emerging evidence highlights a potential role for ACE in treating Alzheimer’s disease (AD) due to its capacity to degrade amyloid beta 1–42 (Aβ1–42)." (PMID 40722848, 2025). "ACE’s Ang II-independent effects involve its broad peptidase activity, including the hydrolysis of amyloid-β1–42, critical in Alzheimer’s disease." (PMID 40722848, 2025). "Overexpression of ACE in myelomonocytes substantially reduced Aβ load and prevented Alzheimer’s disease-like cognitive decline in mice." (PMID 40988601, 2025). "This review examines the role of angiotensin-converting enzyme (ACE) in the context of Alzheimer’s disease (AD) and its potential therapeutic value." (PMID 37427403, 2023). "Central-acting angiotensin-converting enzyme (ACE) inhibitors have been reported to prevent cognitive impairment and decrease β-amyloid-dependent neurodegeneration in animal models of Alzheimer’s disease." (PMID 37630190, 2023). "Clinical observations have also suggested that ACE inhibitors reduce the rate of functional decline in patients with Alzheimer’s disease and/or dementia." (PMID 37630190, 2023). "LRP1B was recently identified as an essential mediator of C1q-induced protection against β-amyloid neurotoxicity in Alzheimer’s disease mouse models, which partly explains how ACE inhibitors reduce β-amyloid-dependent neurodegeneration." (PMID 37630190, 2023). "ACE and Ang II also play a role in Alzheimer’s disease: brain ACE expression was related to Alzheimer’s disease severity and amyloid-beta (Aβ) load and Ang II is responsible for the development of neurovascular damage and dysfunction via the AT1R pathway." (PMID 35565887, 2022). "In mouse models of Alzheimer’s disease and HD, ACE inhibitors and Ang II antagonists were administrated to improve cognitive impairment by reducing mitochondrial oxidants." (PMID 33631722, 2021). "But, while some evidence for a role of ACE in limiting progression of experimental neurodegenerative diseases has been obtained in animals the role of ACE in Alzheimer disease remains controversial, despite being suggested by some clinical studies." (PMID 31316987, 2019). "Increasingly, the actions of ACE and, therefore, angiotensin II within the central nervous system are of increasing interest in the context of Alzheimer’s disease." (PMID 29176997, 2017). "Further to this, losartan, and other ARBs and ACE inhibitors, have been shown to improve outcomes for Alzheimer's Disease patient by improving cerebral blood flow and reducing inflammatory responses." (PMID 24971515, 2014). "Variants in associated with ACE and those associated with MMP3 levels also show association with risk for Alzheimer's disease in the expected directions." (PMID 25340798, 2014). "In the human brain, ACE protein level and activity were found to be increased in the cerebral cortex of patients with Alzheimer’s disease compared with control subjects." (PMID 24618270, 2014). "Activity of ACE-1 is reportedly increased in Alzheimer's disease in direct relationship to parenchymal Aβ amyloid load, raising the possibility that intracerebral ACE levels are upregulated as a response to Aβ accumulation within the brain." (PMID 24826302, 2013). "In contrast, a centrally active ACE inhibitor, perindopril, was reported to prevent cognitive impairment in chronic central hypoperfusion rats and Alzheimer disease model mice." (PMID 23304450, 2012).